GCLC (glutamate-cysteine ligase catalytic subunit)
Diseases named in the same sentence as GCLC in open-access papers (continued):
Sharing a sentence is not in itself a finding about the gene and the disease.
psoriasis (3 papers, 2022 to 2025). An autoimmune condition characterized by red, well-delineated plaques with silvery scales that are usually on the extensor surfaces and scalp. "Genotyping data for six common polymorphisms of the GCLC gene in patients with psoriasis and controls were obtained from our previous study." (PMID 40278165, 2025). "The present study is the first to demonstrate that polymorphisms in the GSTO1 gene, both individually and in combination with GCLC polymorphisms and glutathione-depleting environmental risk factors, contribute to susceptibility to psoriasis." (PMID 40278165, 2025). "The application of the mbmdr methods enabled the identification of epistatic interactions between the polymorphisms of the GSTO1 gene and variants of GCLC in determining the risk of psoriasis." (PMID 40278165, 2025). "Our recent study identified the joint effects of alcohol consumption and GCLC gene polymorphisms on psoriasis risk." (PMID 40278165, 2025). "In females, the impact of polymorphisms in the GSTO1 gene on the risk of psoriasis was more pronounced than that of the GCLC gene." (PMID 40278165, 2025). "This study is the first to demonstrate that polymorphisms in the GSTO1 gene, both individually and in combination with variants of the GCLC gene and alcohol abuse, are associated with an increased risk of psoriasis." (PMID 40278165, 2025). "Sexual dimorphism in the discovered associations of GCLC gene polymorphisms with psoriasis risk is apparently attributed to differences in environmental exposures (i.e., smoking and alcohol abuse) between sexes." (PMID 37374099, 2023). "Our findings of gene–environment interactions indicate that risk factors such as cigarette smoking and alcohol abuse can modify the associations between GCLC gene polymorphisms and the risk of psoriasis." (PMID 37374099, 2023). "We investigated the effect of GCLC gene polymorphisms on psoriasis risk depending on these environmental risk factors in the studied population." (PMID 37374099, 2023). "Since our study was the first to investigate the contribution of GCLC gene polymorphisms to psoriasis risk in relatively small groups of patients, further studies in populations with a larger sample size are required to replicate the observed associations." (PMID 37374099, 2023). "The associations of GCLC gene polymorphisms with clinical manifestations of psoriasis were analyzed and adjusted for sex." (PMID 37374099, 2023). "We analyzed associations between the GCLC gene polymorphisms and the risk of psoriasis in entire groups and groups stratified by sex." (PMID 37374099, 2023). "The present study is the first to show that polymorphisms of the GCLC gene are significantly associated with the risk of psoriasis and related to its clinical features." (PMID 37374099, 2023). "Further genetic association studies are recommended to follow the gene-based approach to look for the link between psoriasis and a wider spectrum of polymorphisms in the GCLC gene." (PMID 37374099, 2023). "Another possible explanation for the sexual dimorphism observed in the associations between GSTO1 and GCLC polymorphisms and psoriasis is that women generally exhibit greater sensitivity to the toxic effects of chemical pollutants compared to men, as evidenced by some studies." (PMID 40278165, 2025). "Therefore, we performed a replication analysis of associations between the studied GCLC gene polymorphisms and psoriasis susceptibility in two large populations from the UK Biobank." (PMID 37374099, 2023). "The aim of this pilot study was to investigate whether single nucleotide polymorphisms (SNP) in the gene encoding the catalytic subunit of glutamate cysteine ligase (GCLC) are associated with the risk and clinical features of psoriasis." (PMID 37374099, 2023). "However, no studies have been designed so far to investigate the role of GCLC gene polymorphisms in psoriasis susceptibility." (PMID 37374099, 2023).
psoriasis (continued). "However, the sex-stratified analysis detected that SNPs rs648595 (OR = 0.56, 95% CI 0.35–0.90; Pperm = 0.017, recessive model) and rs2397147 (OR = 0.54, 95% CI 0.30–0.98; Pperm = 0.05, recessive model) of the GCLC gene were associated with susceptibility to psoriasis in males." (PMID 37374099, 2023). "Therefore, the purpose of our pilot study was to investigate whether common polymorphisms at the gene encoding the catalytic subunit of glutamate cysteine ligase (GCLC) are associated with the risk and clinical features of psoriasis." (PMID 37374099, 2023). "However, we believe that the sexual dimorphism observed in the associations between psoriasis and the SNPs of the GSTO1 and GCLC genes—both individually and in interaction with one another and environmental factors—can be attributed to several reasons." (PMID 40278165, 2025). "In particular, we found that allele rs648595G (this SNP showed the most significant association with psoriasis) is associated with a decreased expression of GCLC in blood, non-sun-exposed suprapubic skin, and sun-exposed lower leg skin." (PMID 37374099, 2023). "Thus, our study supports the causative roles of tobacco smoking and alcohol abuse in the development of psoriasis, and the negative effects of these environmental factors eliminate the protective role of polymorphisms of the GCLC gene against disease risk." (PMID 37374099, 2023). "Genetic polymorphisms of glutamate cysteine ligase that are correlated with a decrease in GCLC mRNA and protein expression, enzyme activity, and GSH content represent attractive markers for studying the molecular mechanisms of psoriasis." (PMID 37374099, 2023).
schizophrenia (3 papers, 2017 to 2022). A major psychotic disorder characterized by abnormalities in the perception or expression of reality. "Polymorphisms of GCLM are associated with a decrease in GCLC expression in hemolytic anemia patients, both a decrease in GSH levels and a subsequent onset of drug resistance in cancer cell lines, and both reduced GCL activity and correspondingly decreased GSH levels in schizophrenia patients." (PMID 35011559, 2022).
steatosis (3 papers, 2017 to 2020). Increased lipid within the cytoplasm of cells. "GCLCh/h mice with a hepatocyte-specific ablation of GCLC developed severe steatosis, although with L-N-acetylcysteine treatment, GCLCh/h mice also display characteristics of fibrosis at age 50 days, and even macronodular cirrhosis at age 120 days." (PMID 33015132, 2020). "While it remains unknown how GCLC regulates mitochondrial function, its deletion in mouse liver leads to striking decreases in mitochondrial function, mitochondrial injury, loss of cellular ATP, and a marked increase in lipid peroxidation, driving steatosis and liver failure." (PMID 28411284, 2017). "Further, GCLC gene-knockout caused GSH depletion, hepatic inflammation, steatosis and liver failure." (PMID 28416740, 2017).
type 1 diabetes (3 papers, 2011 to 2017). "The functional SNPs -675 T → A in CYBA and rs17883901 in GCLC, probably associated with cellular redox imbalances, modulate the risk for renal disease in the studied population of type 1 diabetes patients." (PMID 21962117, 2011). "In the current study, the presence of at least one A allele in -675 T → A SNP and at least one T allele in rs17883901 located, respectively, at the promoter region of the CYBA and GCLC genes modulate the risk for decreased GFR in type 1 diabetes patients even after adjusting for other risk factors." (PMID 21962117, 2011). "However, a few studies have reported that the SNP -129 C/T and the TNR (GAG trinucleotide repeat) polymorphism in the GCLC gene are associated with several clinical phenotypes such as type 1 diabetes, chronic beryllium disease, depression and lung function and growth." (PMID 24693973, 2014). "Frequency of CYBA - 657 T → A (unregistered), GCLC - 129 C → T (rs17883901) and GPX3 - 65 T → C (rs8177412) polymorphisms in type 1 diabetes patients and non-diabetic control subjects." (PMID 21962117, 2011).
type 2 diabetes (3 papers, 2014 to 2023). "This study examined the hypothesis that the levels of vitamin D and LC correlate with those of GSH in the blood of type 2 diabetic patients (T2D), and that vitamin D and LC upregulate glutamate–cysteine ligase (GCLC), which catalyzes GSH biosynthesis, in cultured monocytes." (PMID 24961547, 2014). "Furthermore, reduced expression of GSH synthesizing enzymes, such as GCLC, GSS, and GGT, is associated with lower GSH levels in people with type 2 diabetes mellitus (T2DM)." (PMID 37239011, 2023). "In particular, we found a decreased expression of the GCLC gene in the samples from patients with type 2 diabetes compared with non-diabetic controls in both datasets." (PMID 37569434, 2023).
alcohol abuse (2 papers, 2023 to 2025). The use of alcoholic beverages to excess, either on individual occasions ("binge drinking") or as a regular practice. "Moreover, the vast majority of mbmdr G x E models incorporated the combined effects of alcohol abuse and the polymorphisms of the GSTO1 and GCLC genes on the risk of developing the disease." (PMID 40278165, 2025).
cholestasis (2 papers, 2022 to 2024). Impairment of the bile flow caused by obstruction within the liver, or outside the liver in the bile duct system. "Our data suggest that suppression of Nrf2 mediated GCLC expression is also occurring at early stages (3 days) of BDL-induced cholestasis." (PMID 36378690, 2022).
depression (2 papers, 2014 to 2025). "Once Nrf2 is activated, Keap1 is released from Nrf2 and promotes nuclear translocation of Nrf2, activating the downstream target proteins HO-1, SOD1, GCLC, and GCLM, thus playing a key role in anti-inflammatory and anti-oxidative stress activities of depression." (PMID 40308754, 2025).
diabetic cardiomyopathy (2 papers, 2022 to 2025). Diabetic cardiomyopathy is a disorder of the heart muscle in people with diabetes. "The present study found that quercetin promoted the nuclear translocation of Nrf2, increased the expression levels of the downstream antioxidant factors HO-1 and GCLC, cleared the accumulation of intracellular ROS, and inhibited the process of pyroptosis in diabetic cardiomyopathy." (PMID 36624860, 2022).
ischemic stroke (2 papers, 2023 to 2024). A stroke disorder caused by obstruction of blood flow to the brain, due to thrombotic (local blood clot formation) or embolic (due to a blood clot or other material traveling from another site) event. "Thus, it would be worth assessing whether NQO1 and GCLC are induced in MG after ischemic stroke and determining their effects on modulating ischemic brain injury." (PMID 39469715, 2024).
liver disease (2 papers, 2025). "Moreover, Lira significantly upregulated ferroptosis-related proteins, including ACSL1, GCLM, and GCLC, indicating enhanced glutathione production, which protects cells from ferroptosis, a lipid peroxidation-related cell death process associated with liver disease." (PMID 41377138, 2025).
malaria (2 papers, 2014 to 2023). Malaria is a serious and sometimes fatal disease caused by a parasite that commonly infects a certain type of mosquito which feeds on humans. "There is strong literature evidence for ICAM1, as well as another gene identified herein, GCLM, and its associated gene, GCLC being potential molecular mediators for the pathology of malaria." (PMID 37287037, 2023). "Numerous studies have reported on associations of the genetic variants in GSR, GCLC, HMOX1 and SOD2 with oxidative stress related disorders and conditions including malaria." (PMID 24693973, 2014). "In conclusion, the present study has identified several polymorphisms in GCLC, GSR and HMOX1 genes that are associated with oxidative stress status in the blood plasma of two-year old children from a malaria endemic region." (PMID 24693973, 2014).
non-small cell lung carcinoma (2 papers, 2020 to 2025). A group of at least three distinct histological types of lung cancer, including non-small cell squamous cell carcinoma, adenocarcinoma, and large cell carcinoma. "Based on these findings, we proposed GCLC, glutathione peroxidases, and glutathione as possible targets to regulate EMT in non-small cell lung cancer." (PMID 32850411, 2020).
oral cancer (2 papers, 2021). "For example, sulforaphane can target Nrf2 and the Nrf2 target genes NQO1 and GCLC to prevent oral cancer, and a preclinical trail has been performed to study its chemopreventive activity for oral cancer." (PMID 33841137, 2021). "Accordingly, the antioxidant signaling gene expression for mRNA, including NFE2L2, GCLC, TXN, CAT, SOD1, HMOX1, and NQO1, was examined for POMx-incubated oral cancer cells." (PMID 34356350, 2021). "Similar to the present study, the mRNA expressions for several antioxidant genes (NFE2L2, GCLC, TXN, CAT, SOD1, HMOX1, and NQO1) were downregulated at 24 h POMx for three oral cancer cell lines." (PMID 34356350, 2021).
pancreatic cancer (2 papers, 2011 to 2017). "NRF2 knockdown markedly reduced the expression of NRF2 and glutamate-cysteine ligase catalytic subunit (GCLC) in cell lines established from pancreatic cancers." (PMID 28671577, 2017). "Keap1, Nrf2 and the Nrf2 target genes AKR1c1 and GCLC were detected in a panel of five pancreatic cancer cell lines." (PMID 21489257, 2011).
acute liver failure (1 paper, 2024). Rapid deterioration of liver function causing encephalopathy and coagulopathy. "In APAP-induced acute liver failure patients (GSE74000), IKBKG levels decreased, and Nrf2 target genes were also repressed (i.e., HMOX1, PRDX1, TXNRD1, GPX4, GPX1, GCLC, GCLM, and NQO1)." (PMID 38505605, 2024).
AIDS (1 paper, 2012). A syndrome resulting from the acquired deficiency of cellular immunity caused by the human immunodeficiency virus (HIV). "Taken together, the results indicate that a regulatory polymorphism in GCLC that affects mRNA expression modify risk of developing SMX-induced hypersensitivity in HIV/AIDS patients." (PMID 22824134, 2012). "In this study, we have found rs761142 T > G in GCLC to be significantly associated with SMX-induced hypersensitivity in HIV/AIDS patients, with each copy of the minor G allele increasing risk nearly 2 fold." (PMID 22824134, 2012). "We have identified a single nucleotide polymorphism in GCLC that was significantly associated with reduced GCLC mRNA expression and with SMX-induced hypersensitivity in HIV/AIDS patients." (PMID 22824134, 2012). "rs761142 in GCLC was found to be associated with reduced GCLC mRNA expression and with SMX-induced hypersensitivity in HIV/AIDS patients." (PMID 22824134, 2012). "Given the important role of GCLC in scavenging reactive metabolites, variants that reduce GCLC expression have a plausible role in increasing risk of developing SMX-induced hypersensitivity, especially in HIV/AIDS patients with already compromised GCLC function." (PMID 22824134, 2012). "Whether the GCLC polymorphisms are associated with SMX-induced hypersensitivity in non-HIV/AIDS patients will require further investigation." (PMID 22824134, 2012).
Alzheimer disease (1 paper, 2023). A progressive, neurodegenerative disease characterized by loss of function and death of nerve cells in several areas of the brain leading to loss of cognitive function such as memory and language. "SOD1 has not been reported in AAA, but when treated with hydroxyl ethanol, it inhibits Ang II-induced Alzheimer’s disease, decreases the expressing of NF-κB, P65, TNF-α, and IL-1β, and increases the conveying of SOD1, MMP9, and GCLC in mice." (PMID 37737183, 2023).
Atrophy (1 paper, 2020). Any weakening or degeneration, especially through lack of use. "GCLC deficiency causes motor neuron loss, spinal cord atrophy and defective gait." (PMID 32801000, 2020).
brain cancer (1 paper, 2024). A primary or metastatic malignant neoplasm affecting the brain. "To gain new insights into the impact of disease on co-expression of EGFR and GCLC genes, we analyzed the correlation between EGFR and GCLC co-expression in human normal brain and brain cancer tissues." (PMID 39001381, 2024). "EGFR and GCLC displayed a significant positive correlation in normal brain tissue (Pearson R = 0.317, padj = 1.8 × 10−4), which strikingly decreased to a near-zero value in brain cancer (Pearson R = 0.0098, padj = 4.5 × 10−4)." (PMID 39001381, 2024). "As expected, scatter plot analysis of EGFR and GCLC co-expression showed that the distribution of EGFR tissue expression in normal brain samples (N = 3198) shifts toward higher expression levels in brain cancer tissue (N = 2750)." (PMID 39001381, 2024).
breast tumors (1 paper, 2024). "Pair-wise mRNA expression correlation analysis in human breast tumors from TCGA cohort showed a positive correlation between ZMYND8 and antioxidant genes including NQO1, GPX2, GCLC, GCLM, TXNRD1, and SRXN1." (PMID 38488001, 2024).
carbon monoxide poisoning (1 paper, 2025). A poisoning that is caused by exposure to carbon monoxide. "Besides ferroptosis, previous researches have also demonstrated the neuroprotective roles of the Nrf2/GCLC and GSK-3β/Tau pathways in acute carbon monoxide poisoning." (PMID 40653468, 2025).
cholangiocarcinoma (1 paper, 2025). A carcinoma that arises from the intrahepatic biliary tree (intrahepatic cholangiocarcinoma) or from the junction, or adjacent to the junction, of the right and left hepatic ducts (hilar cholangiocarcinoma). "In cholangiocarcinoma (CG), the m5C methyltransferase can be lactylated at K508 to significantly enhance its activity, which enhances the stability of the mRNA of GCLC, leading to the upregulation of GCLC, which induces the production of glutathione (GSH)." (PMID 41285721, 2025).
colorectal tumors (1 paper, 2025). "Notably, analysis of the TCGA database revealed that GCLC is highly expressed in colorectal tumors." (PMID 40113760, 2025).
E. coli infection (1 paper, 2025). "E. coli infection activates GSK-3β through dephosphorylation at Ser9, active GSK-3β binds and degrades NRF2 via the proteasome pathway, and NRF2 suppression disrupts antioxidant defenses (SLC7A11/GPX4 and GCLC/GSH) and iron homeostasis (FTH1), triggering ferroptosis in BEECs." (PMID 41413615, 2025).
endometritis (1 paper, 2025). An acute or chronic, usually bacterial infectious process affecting the endometrium. "The expression of both the GCLC and NQO1 genes and proteins also decreased in the endometritis group." (PMID 41413615, 2025).
glomerular disease (1 paper, 2015). "The current study, for the first time, demonstrates that the glomerular disease in a mouse model of anti-GBM-GN is associated with impaired Nrf2 activation (reduced nuclear content) along with low levels of GCLc, GCLm, and GPx1." (PMID 25785827, 2015).
HIV-1 infection (1 paper, 2016). The type species of lentivirus and the etiologic agent of acquired immunodeficiency syndrome (AIDS). "Decreased levels of GSH in individuals with HIV-1 infection were accompanied by diminished levels of enzymes, such as GCLC and GSS in the red blood cells." (PMID 27335804, 2016). "These novel findings add significance to our previous findings that individuals with HIV-1-infection have low levels of GSH, GCLC and GSS in the red blood cells isolated from the peripheral blood." (PMID 27335804, 2016).
lactic acidosis (1 paper, 2013). Metabolic acidosis characterized by the accumulation of lactate in the body.
neck cancer (1 paper, 2020). "Also, GCLC activation is associated with anti-tumor drug resistance in breast, lung, liver, head, and neck cancer." (PMID 32850411, 2020).